IL10 (interleukin 10)
Diseases named in the same sentence as IL10 in open-access papers (continued):
Sharing a sentence is not in itself a finding about the gene and the disease.
prediabetes (continued). "This study hypothesized that opioid peptides and their receptors combined with the immune cytokines (IL-6 and IL-10) affected the IR parameters in prediabetes patients." (PMID 34099024, 2021). "Increased level of IL-10 in prediabetes and T2DM subjects in our study was in disagreement with these findings, which could be explained by high levels of inflammatory cytokines appearing in early stage of T2DM." (PMID 27478850, 2016). "We hypothesize that opioid peptides (endomorphin-2 (EM2), and β-endorphin (βEP)), and their receptors (μ-opioid receptors (MOR) and κ-opioid receptors (KOR)), in addition to the inflammatory cytokines (IL-6) and anti-inflammatory cytokine (IL-10), affect IR parameters in patients with prediabetes." (PMID 34099024, 2021). "The IL-6, IL-10, β-endorphin, MOR, and endomorphin-2 were higher in the prediabetes subgroups than the control group." (PMID 34099024, 2021). "The only exceptions were interleukin 10 (IL10) and interleukin 17A (IL17A) levels, which were significantly lower in individuals with prediabetes." (PMID 33658065, 2021). "Another collection of increased IL-10 and zLnEM2 / KOR can be used with reasonable precision (71.2%) to predict prediabetes+IR." (PMID 34099024, 2021). "Our data showed increased levels of hypersensitivity C-reactive protein (hs-CRP), interleukin (IL-4), IL-10, and tryptase in prediabetes subjects and hs-CRP, immunoglobulin E (IgE), IL-4, and IL-10 in T2DM subjects." (PMID 27478850, 2016). "Similarly, IL-10 levels were significantly lower in T2DM than in controls (p< 0.001) and prediabetes (p< 0.001) but increased in the T2DM-HT group (p = 0.02)." (PMID 37383391, 2023). "No significant variation of cytokines was observed between prediabetes and control group for IL-6, IL-10, IL-17A, IL-4, IL-8, IFN-γ, and TNF-α." (PMID 37457235, 2023). "In a previous study, relative to healthy controls, the serum IL-10 level is elevated in T2DM but not in prediabetes." (PMID 34099024, 2021). "The second regression analysis showed that the combination of IL-10 and zLnEM2/KOR were the best predictors of prediabetes+IR versus prediabetes−IR (χ2 = 14.780, df = 7, p = 0.031, Nagelkerke = 0.364) with an accuracy of 71.2%, sensitivity of 74.4%, and specificity of 72.7%." (PMID 34099024, 2021). "The IL-6, IL-10, βEP, MOR, and EM2 were higher in the prediabetes." (PMID 34099024, 2021). "To examine these hypotheses, we measured serum levels of some opioids proteins and receptors in addition to IL-6 and IL-10 levels in prediabetes patients who have/have not an IR state and compared with the healthy controls." (PMID 34099024, 2021).
pulmonary hypertension (16 papers, 2010 to 2025). Increased pressure within the pulmonary circulation due to lung or heart disorder. "Preoperative echocardiographic pulmonary artery systolic pressure was found to be associated with the levels of IL-6 and IL-10 after surgery in pulmonary hypertension patients." (PMID 40020755, 2025). "Elevated blood levels of IL-10 were associated with pulmonary hypertension in newborns." (PMID 39529072, 2024). "Direct determination of PH in COPD is traumatic, so it is of great clinical significance to detect hs-CRP, IL-6, IL-10, and ET-1 to monitor pulmonary hypertension." (PMID 35186226, 2022). "In experimental studies in rats, IL-10 expression protected against monocrotaline-induced pulmonary hypertension." (PMID 34442052, 2021). "Much of the experimental data in the literature, however, suggest a beneficial role for IL-10 in pulmonary hypertension." (PMID 32117582, 2020). "Subsequent influence on the polarization of macrophages in the lung remains important, as a shift to an IL-10 productive phenotype has been shown to be protective against hypoxia-induced pulmonary hypertension." (PMID 30081463, 2018). "In addition, IL-10 prevented the development of monocrotaline-induced pulmonary arterial hypertension in rats." (PMID 20462420, 2010). "The Nef constructs derived from HIV-pulmonary hypertensive donors demonstrated significant increases in Th1 cytokines IL-2, IL-12p70, and IFNg, as well as anti-inflammatory IL-10, but did not elicit innate immunity cytokines IL-1b or TNFa." (PMID 40559196, 2025). "Patients under a pulmonary arterial hypertension target therapy with prostacyclin agonists showed higher levels of IL-10 compared to patients without such therapy." (PMID 31024947, 2019). "Alternatively, IL-10 may downregulate MHC class II presentation to the cell surface, leading to specific unresponsiveness of T cells to potential alloantigens involved in the development of pulmonary hypertension." (PMID 30081463, 2018).
renal failure (16 papers, 2017 to 2025). "Genotype frequencies of IL-10 −1082 (A/G) promoter polymorphism in HUS I + II vs. HUS III patients: risk analysis of the severity of kidney failure." (PMID 37425258, 2023). "Resident cells, such as mesangial and endothelial cells, produce IL-10 that acts as a cell growth factor inducing changes in the intraglomerular and tubulointerstitial structures that could alter normal function, generate microalbuminuria and proteinuria, and lead to kidney failure." (PMID 37425258, 2023).
SARS-CoV infection (16 papers, 2006 to 2025). "In one study of 128 convalescent patients with SARS-CoV infection, effective T cell responses were shown to be significantly associated with higher neutralizing antibody and with more serum Th2 cytokines (IL-4 and IL-10) detected in fatal group." (PMID 34341947, 2021). "IL-10, a cytokine associated with Th-2 adaptive immune response that represses IFNγ secretion, was associated with poor outcome in the early stage of SARS-CoV infection." (PMID 24551142, 2014). "Previously, higher expression of pro-inflammatory cytokine levels (IFN-α, TNF, IL-6, IL-8, IL-10, and IP-10) were described in monocyte-derived macrophages in SARS-CoV infections." (PMID 34539631, 2021). "During the process of SARS-CoV infection, there was a cytokine storm in patients including IL-1, IL-2, IL-4, IL-6, IL-8, IL-10, IFN-γ, TNF-α and TGF-β1." (PMID 18312678, 2008). "SARS-CoV infection increases cytokine expression (e.g., IFN-γ, IL-1, IL-6, IL-10, IL-12, and IL-16) dramatically, and T lymphocytes and their CD4+ and CD8+ T cells subsets are decreased after the onset of infection." (PMID 33770147, 2021). "Abnormalities in the production levels of several cytokines such as IL-1, IL-2, IL-4, IL-6, IL-8, IL-10, IFN-γ, TNF-α and TGF -β1 were detected in patients with SARS-CoV infection." (PMID 32917282, 2020). "Disease severity is associated with increases in peripheral blood cytokines among which interleukin 10 (IL-10) increases particularly early and independent of patient age, which is not seen in active SARS-CoV infection." (PMID 33746948, 2021).
squamous cell carcinoma (16 papers, 1999 to 2025). A carcinoma arising from squamous epithelial cells. "This is compatible with broad literature where NSCLC patients generally exhibit low IL-10 expression, particularly in squamous cell carcinoma and adenocarcinoma, as shown by mRNA downregulation in tumor regions." (PMID 41020868, 2025). "Other serum biomarkers such as AFP-L3, DCP, interleukin-6, interleukin-10, and squamous cell carcinoma antigen were also investigated, while these serum-based tests lack adequate sensitivity and specificity for effective surveillance." (PMID 36213826, 2022). "In this context, using squamous cell carcinoma in the proposed in vitro model, the myoepithelial cells appeared to have favored tumor growth via the production of IL-6 and IL-10 stimulated by the malignant cells, in a paracrine way." (PMID 25435982, 2015). "Our earlier work reported DER in a nonmetastatic squamous cell carcinoma (SCC) murine model that showed improved radiation-induced tumor growth delay by the pan-NOS inhibitor L-NAME (DER 1.8), which involved abated IL-10 expression and increased CD8+ T cell number and activation." (PMID 38912586, 2024).
unstable angina (16 papers, 2008 to 2026). "A lower IL-10 mRNA production was observed in patients with signs of unstable angina (UA) when compared with those who were exhibiting symptoms of stable angina (SA)." (PMID 34835155, 2021). "Similar results to these experimental data were reported by clinical trials showing that patients with ACS have significantly reduced IL-10 levels than those with stable angina." (PMID 34760045, 2021). "Regular vigorous intensity, interval training increased IL‐10 levels in a 6‐month RCT among angina patients." (PMID 27485297, 2016). "It has been shown that plasma concentrations of cytokines produced by Th1 (IFN-γ and IL-2) were significantly higher than those synthesized by Th2 lymphocytes (IL-10) in patients with ACS when compared to patients with stable angina." (PMID 27563892, 2016). "We have previously reported that patients with unstable angina had significantly lower blood IL-10 concentrations than those with stable angina." (PMID 26504600, 2015). "There are lower serum IL-10 concentrations in patients with unstable angina compared with those who had chronic angina." (PMID 25329057, 2014). "Additionally, the TNF‐α:IL‐10 ratio was notably higher in patients with unstable angina compared to control patients." (PMID 39801756, 2025). "Moreover, we found elevated basal serum concentrations of activated TGF β1 and lower IL-10 levels in patients with recurrent angina events or restenosis of the target lesion at the 6-month follow-up." (PMID 25253465, 2014). "Exogenous IL‐10 significantly reduced TNF‐α and MMP9 levels in peripheral blood mononuclear cells of patients with unstable angina, suggesting that a decreased serum level of IL‐10 could be a marker of plaque instability and predict a poor prognosis after an acute ischemic event." (PMID 39801756, 2025).
urinary tract infection (16 papers, 2009 to 2025). "Urinary tract infection (UTI) caused by uropathogenic Escherichia coli (UPEC) engages interleukin-10 (IL-10) as an early innate immune response to regulate inflammation and promote the control of bladder infection." (PMID 31776239, 2019). "They spatially co-localise with macrophages and regulate their polarization and function, promoting an anti-inflammatory phenotype, in-part via interleukin-10 production, with effects on bacterial clearance during urinary tract infection." (PMID 37925420, 2023). "CD4+Tbet+IFN-γ+ and CD4+FoxP3+IL-10+ T cell populations were decreased in HbSS subjects with asymptomatic urinary tract infections." (PMID 34239376, 2021). "Interleukin-10 is part of the immune response to urinary tract infection (UTI) due to E. coli, and it is important in the early control of infection in the bladder." (PMID 31776239, 2019). "IMPORTANCE Interleukin-10 is part of the immune response to urinary tract infection (UTI) due to E. coli, and it is important in the early control of infection in the bladder." (PMID 31776239, 2019). "We have recently shown that MV140, a sublingual PBP formulated with a different composition of whole‐inactivated bacteria to treat recurrent urinary tract infections, also generates Th1, Th17 and IL‐10 immune responses." (PMID 28799230, 2018). "Studies in recent years have defined a key anti-inflammatory role for Interleukin-10 (IL-10) in urinary tract infection mediated by UPEC and other uropathogens." (PMID 24155979, 2013). "HbSS subjects with asymptomatic urinary tract infections had elevated plasma levels of interferon gamma (IFN-γ) and interleukin (IL)-10." (PMID 34239376, 2021).
coccidiosis (15 papers, 2019 to 2024). A parasitic infection caused by Coccidia. "When comparing two different chicken lines with different coccidiosis susceptibility, susceptible chickens (line 15I) showed greater expression levels of IL-10 in the spleen and gut compared to the resistant chickens (line C.B12) following E. maxima infection." (PMID 35214673, 2022). "The OEO has an anti-inflammatory effect and down-regulates IL-10 expression in the birds, acting as a possible antibiotic substitute to control coccidiosis." (PMID 39457937, 2024). "This implies that broilers had a better intestinal immune response (lower possibility of parasite-induced IL-10 immune escape) to coccidiosis challenge with the support of both d 1 vaccination and optimal sulfur amino acid supplementation at ≥0.8% SID M+C." (PMID 36863121, 2023). "Using a subclinical model of Eimeria infection, we demonstrated that the immunotherapeutic efficacy of anti-IL-10 to coccidiosis was highly affected by dietary SID M+C levels." (PMID 35949200, 2022). "In the future, if anti-IL-10 is commercialized as a new approach for coccidiosis control, then considerable benefits will be obtained by providing optimal sulfur amino acids as a dietary supplement to enhance the effectiveness of anti-IL-10." (PMID 35949200, 2022). "Oral antibodies to IL-10 have previously been shown to confer protection against intestinal lesions and growth suppression in broilers with coccidiosis." (PMID 35949200, 2022). "In the present study, the immunotherapeutic effects of anti-IL-10 to coccidiosis were confirmed using a model of Eimeria infection." (PMID 35949200, 2022). "Interaction effects were detected on duodenum (SID M+C × coccidiosis, P = 0.029), jejunum (coccidiosis × anti-IL-10, P = 0.040), and cecum (coccidiosis × anti-IL-10, P = 0.004) luminal IFN-γ concentrations." (PMID 35949200, 2022). "In jejunum luminal, an interaction between coccidiosis and anti-IL-10 was observed for T-IgA (P = 0.022)." (PMID 35949200, 2022). "In comparison to D3 at the same level of supplemental dietary inclusion, it has likewise been shown that the expression of IL-10 increased and IL-1β decreased in response to 2760 IU/kg of 25OHD3 in broilers challenged with coccidiosis." (PMID 36230268, 2022). "During the periods of d 15 to 21 and d 11 to 21, interactions (P ≤ 0.05) were detected among SID M+C, coccidiosis, and anti-IL-10 effects on body weight gain and feed intake." (PMID 35949200, 2022). "Our findings underscore the importance of providing sufficient essential nutrients to support the anti-IL-10 induced immunity against coccidiosis." (PMID 35949200, 2022). "In the duodenal lumen, an interaction among SID M+C, coccidiosis, and anti-IL-10 was observed for T-IgA (P = 0.012)." (PMID 35949200, 2022). "IL10 has been widely studied in chicken coccidiosis and its upregulation in serum was regarded as a symbol of intestinal inflammatory damage caused by Eimeria coccidia." (PMID 33192575, 2020). "In coccidiosis, IL-10 is considered to play an important role in evasion of the host immune response." (PMID 31824509, 2019). "When both dietary (69 μg/kg feed) and in ovo (2.4 μg) sources of 25(OH)D3 were individually administered in normal or coccidiosis-infected poultry species, positive effects have been observed on the expressions of anti-inflammatory (IL-1β) and pro-inflammatory response (IL-10 and TGF-β4) genes." (PMID 39794953, 2024). "In addition, in vivo studies showed that QCC reduced blood stool in chickens with coccidiosis, restored cecal injury, and significantly reduced the mRNA and protein expression levels of IL-1β, IL-10, and IFN-γ in ceca (p < 0.01)." (PMID 38496310, 2024). "The intricate interplay of IL-10 in regulating inflammation underscores its importance in maintaining immune homeostasis, especially in the context of intestinal diseases such as necrotic enteritis and coccidiosis." (PMID 38787208, 2024).
coccidiosis (continued). "The RNA-sequencing results suggested that early activation of IFN-γ, IL-10, and immune-related genes, including IL-21, may be the key to resistance to coccidiosis." (PMID 35214673, 2022). "However, the specific functions of IL-10 and IL-17 in the immunity to coccidiosis requires further investigation." (PMID 33944773, 2021). "IL-10 was widely believed to be involved in the development of coccidiosis." (PMID 33192575, 2020). "IL-10 has been considered to play an important role to evade host immune response in coccidiosis." (PMID 30972060, 2019). "by Treg cells is critical and IL-10 contributes to pathogenesis in coccidiosis." (PMID 30972060, 2019). "Interestingly, in this study, when broilers were vaccinated (d 1) and subsequently infected (d 14) with coccidiosis, the d 21 intestinal luminal IL-10 production was increased only in those fed 0.6% SID M+C, a level that is obviously deficient for growth performance." (PMID 36863121, 2023). "In the current study, immunized birds exert enhanced secretion patterns of IL-10 and TGF-β, suggesting that Th9-related immune responses were essential in host immunity against coccidiosis." (PMID 35693811, 2022). "For coccidiosis, upregulation of IFN-γ and relative downregulation of IL-10 appear to be features of birds selected for disease resistance." (PMID 33445562, 2021). "Compared with DIM, ETDIM induced greater IL-10 expression after 1 DPI, thus suggesting that DIM induces more Treg cells in coccidiosis." (PMID 30972060, 2019). "Coccidiosis challenge increased (P < 0.05) luminal concentrations of IL-10 and IFN-γ in the duodenum and jejunum, regardless of dietary SID levels." (PMID 36863121, 2023). "In the parallel study, in which broilers were not vaccinated with coccidiosis on d 1, coccidiosis challenge on d 14 stimulated intestinal luminal IL-10 production of d 21 broilers regardless of dietary SID M+C levels." (PMID 36863121, 2023). "Regardless of dietary SID M+C levels, coccidiosis induced increased jejunum luminal T-IgA concentration only with the presence of anti-IL-10." (PMID 35949200, 2022). "CD4 T lymphocytes in murine coccidiosis may produce soluble cytokines such as IFN-γ and IL-10." (PMID 38751432, 2024). "Notably, in the current coccidiosis model, Eimeria-infection significantly induced intestinal luminal anti-Eimeria IgA production regardless of dietary anti-IL-10 and SID M+C levels." (PMID 35949200, 2022). "However, intestinal luminal IL-10 concentrations were increased (main effect, P < 0.001) in broilers with coccidiosis; regardless of dietary SID M+C and anti-IL-10 supplements." (PMID 35949200, 2022).